TADA2B (transcriptional adaptor 2B)
Description:
Coactivates PAX5-dependent transcription together with either SMARCA4 or GCN5L2.
Synonyms: ADA2B; MGC21874; ADA2(beta)
Tractability: PROTAC: ubiquitination databases record sites on it; its protein half-life has been measured.
Gene: Protein-coding gene on chromosome 4 (7,041,899 to 7,057,952, forward strand). Ensembl gene ENSG00000173011.
Subcellular location: Nucleus
Subcellular location (Human Protein Atlas): Nuclear speckles
Pathways (Reactome):
Chromatin organization: HATs acetylate histones
Metabolism of proteins: Ub-specific processing proteases
Gene Ontology:
Molecular function: protein binding; chromatin binding; transcription coactivator activity; zinc ion binding
Biological process: chromatin remodeling; positive regulation of DNA-templated transcription; regulation of DNA repair; regulation of RNA splicing; regulation of transcription by RNA polymerase II
Cellular component: SAGA-type complex; nucleoplasm; SAGA complex; nucleus
Genetic constraint (gnomAD): Loss-of-function variants: 13 observed, 27.26 expected, observed/expected ratio (o/e) 0.48, 90% interval 0.31 to 0.76. The upper end of that interval is the gene's LOEUF score, 0.76, which puts it in group 3 of 6, group 1 being the genes least tolerant of losing a copy. Missense variants: 442 observed, 535.08 expected, observed/expected ratio (o/e) 0.83, 90% interval 0.76 to 0.89. Synonymous variants: 240 observed, 227.31 expected, observed/expected ratio (o/e) 1.06, 90% interval 0.95 to 1.17.
Homologues: Orthologues: chimpanzee TADA2B (100% identical), macaque TADA2B (99% identical), mouse Tada2b (99% identical), rat Tada2b (99% identical), pig TADA2B (98% identical), guinea pig TADA2B (97% identical), dog TADA2B (96% identical), tropical clawed frog tada2b (91% identical), zebrafish tada2b (87% identical), Drosophila melanogaster Ada2b (40% identical), Caenorhabditis elegans ada-2 (24% identical). Paralogues in human: TADA2A (30% identical).
Diseases named in the same sentence as TADA2B in open-access papers:
TADA2B is named in the same sentence as 12 diseases in open-access papers, as found by Europe PMC text mining. Sharing a sentence is not in itself a finding about the gene and the disease. The quoted sentences say what the papers report.
melanoma (1 paper, 2023). A malignant, usually aggressive tumor composed of atypical, neoplastic melanocytes. "The lentivirus-encapsulated GeCKO library was transfected into melanoma cells, and new melanoma resistance-related genes NF2, CUL3, TADA2B, and TADA1 were identified by vemurafenib resistance screening." (PMID 37834313, 2023).
neuroblastoma (1 paper, 2024). Neuroblastoma (NB) is the most common solid, extracranial childhood tumor. "We find that loss of SAGA complex KAT activity in MYCN-amplified neuroblastoma, through modulation of TADA2B, leads to a rapid and global loss of acetylation on H3K9, including in the promoters of actively transcribed genes." (PMID 38820154, 2024). "We report that the acetyltransferase activity of the SAGA complex is required to maintain the oncogenic state in neuroblastoma and that impairing this activity either through TADA2B KO/degradation or through combined loss of KAT2A/KAT2B impairs neuroblastoma cell growth." (PMID 38820154, 2024). "We next sought to interrogate where in the genome the SAGA complex is recruited in MYCN-amplified neuroblastoma, using TADA2B as a proxy for the SAGA complex." (PMID 38820154, 2024). "We first confirmed that knockout (KO) of TADA2B using multiple independent sgRNAs impaired growth in three MYCN-amplified neuroblastoma models in low throughput." (PMID 38820154, 2024). "Among the most enriched differential gene dependencies observed in MYCN-amplified neuroblastoma as compared to all other solid tumor lineages were TADA2B, TADA1, SUPT20H, and TAF5L, along with several other members of the core and KAT modules." (PMID 38820154, 2024). "We found that neuroblastoma cells with CRISPR-mediated KO of TADA2B accumulated in G0-G1 phase." (PMID 38820154, 2024). "Thus, we focused our efforts on TADA2B to specifically interrogate the role of the SAGA complex in MYCN-amplified neuroblastoma." (PMID 38820154, 2024). "Thus, this redundancy may explain why MYCN-amplified neuroblastoma depends on TADA2B, which is required for full KAT activity." (PMID 38820154, 2024). "To interrogate the possibility that KAT2A and KAT2B are functionally redundant in this context, we used two MYCN-amplified neuroblastoma cell lines, KELLY and NB1, that depend on TADA2B but have high and low KAT2B expression, respectively." (PMID 38820154, 2024). "Given the observation that TADA2B dependency is strongly enriched in MYCN-amplified neuroblastoma and that TADA2B occupancy is enriched for the MYCN CANNTG motif, we next sought to investigate whether TADA2B colocalizes with MYCN on chromatin." (PMID 38820154, 2024). "However, TADA2B, the strongest outlier dependency in MYCN-amplified neuroblastoma, is uniquely found in the SAGA complex and is required for its KAT activity." (PMID 38820154, 2024).
cancer (1 paper, 2024). A tumor composed of atypical neoplastic, often pleomorphic cells that invade other tissues. "Although our findings cannot be directly compared to prior work in MYC-driven cancers, our studies clearly show that perturbing TADA2B impairs SAGA complex KAT activity regardless of which KAT is associated." (PMID 38820154, 2024).
infection (1 paper, 2024). The state of being infected such as from the introduction of a foreign agent such as serum, vaccine, antigenic substance or organism. "To further confirm that the observed effects were the result of TADA2B loss, we also compared these expression signatures with constitutive CRISPR KO of TADA2B using two distinct sgRNAs 7 and 12 days after infection." (PMID 38820154, 2024).
TADA2B also shares sentences with these, for which no sentence is quoted: acute myeloid leukemia (1 paper); anemia (1); eating disorder (1); leukemia (1); lymphoma (1); psychiatric disorder (1); sarcoma (1); tumor (1).